SLCO1B7 (solute carrier organic anion transporter family member 1B7 (putative))
Synonyms: LST3; SLC21A21
Gene: Transcribed unprocessed pseudogene on chromosome 12 (20,962,768 to 21,090,106, forward strand). Ensembl gene ENSG00000205754.
Subcellular location: Cell membrane
Diseases named in the same sentence as SLCO1B7 in open-access papers:
SLCO1B7 is named in the same sentence as 8 diseases in open-access papers, as found by Europe PMC text mining. Sharing a sentence is not in itself a finding about the gene and the disease. The quoted sentences say what the papers report.
lung carcinoma (2 papers, 2023 to 2025). "Overall, AR plays an important role in suppressing lung cancer progression by altering the circ-SLCO1B7/TPD52 signaling axis." (PMID 37564195, 2023). "Next, we investigated the contribution of circ-SLCO1B7 to the cell invasion of lung cancer cells using transwell assay." (PMID 37564195, 2023). "Taken together, these findings support the notion that AR functions as a tumor suppressor of lung cancer progression through the regulation of circ-SLCO1B7." (PMID 37564195, 2023). "The expression level of circ-SLCO1B7 was indeed increased in lung cancer samples as compared to the normal counterparts." (PMID 37564195, 2023). "The results demonstrated that loss of AR promoted lung cancer metastasis, however, when shcirc-SLCO1B7 was introduced in combination with shAR, it effectively blocked shAR-mediated lung cancer metastasis." (PMID 37564195, 2023). "The in vivo data also validated the functional contribution of AR/circ-SLCO1B7/miR-139-5p/TPD52 axis to lung cancer progression." (PMID 37564195, 2023). "Specifically, we found that AR-regulated circ-SLCO1B7, a circular RNA molecule, plays a significant role in lung cancer cell invasion and response to cisplatin." (PMID 37564195, 2023). "In our study, we confirmed that TPD52 indeed acts as an oncogene and is regulated by the AR/circ-SLCO1B7/miR-139-5p signaling pathway, promoting lung cancer progression." (PMID 37564195, 2023). "Taking together, we conclude that circ-SLCO1B7, as a circular RNA, enhances the cell invasion of lung cancer." (PMID 37564195, 2023). "However, our data also indicated that the reversal of AR regulated TPD52 expression by miR-139-5p was only partial, suggesting that sponging miR-139-5p is just one of the signaling pathways involved in the AR-circ-SLCO1B7-mediated lung cancer progression." (PMID 37564195, 2023). "Therefore, we decided to focus on TPD52 for further investigation regarding its potential links to AR, circ-SLCO1B7 and miR-139-5p in lung cancer progression." (PMID 37564195, 2023). "As expected, our quantification analyses were consistent with the IVIS signal observed earlier, demonstrating a higher number of metastatic foci in the shAR group compared to the control group, which could be attenuated in counterparts bearing lung cancer with depletion of both AR and circ-SLCO1B7." (PMID 37564195, 2023). "The results demonstrated that hsa_circ_0008705 (circ-CABYR) and hsa_circ_0025583 (circ-SLCO1B7) consistently displayed changes in expression in response to AR manipulation, suggesting a potential regulatory role of AR in modulating the expression of these circRNAs in lung cancer cells." (PMID 37564195, 2023). "Collectively, the results from our study suggest that AR can suppress lung cancer cell invasion and increase DDP response by modulating the circ-SLCO1B7/miR-139-5p/TPD52 signaling pathway." (PMID 37564195, 2023). "The decreased expression of circ-SLCO1B7 alleviates its sponge as miR-139-5p, allowing miR-139-5p to suppress TPD52 messenger RNA and leading to the retarded lung cancer progression." (PMID 37564195, 2023).
neutropenia (2 papers, 2017 to 2019). A decrease in the number of neutrophils found in the blood. "We now know that the genetic etiology of clozapine-associated neutropenia is complex and is likely to involve variants from several genes including HLA-DQB1, HLA-B and SLCO1B3/SLCO1B7." (PMID 30767710, 2019).
ovarian carcinoma (1 paper, 2018). A malignant neoplasm originating from the surface ovarian epithelium. "Furthermore, the present findings suggested two networks of SLCO and ABC-transporter coding genes (SLCO2B1/ABCC3 and ABCB2/ABCB3/ABCC3/HER-2) and demonstrated the expression of SLCO1B7 in ovarian cancer samples." (PMID 30131693, 2018).
Pancreatic Cancer (1 paper, 2017). "Along with six other top DEGs, i.e. TINAG, LINC00460, UGT1A9, SLCO1B7, HOTTIP, and ALCO1B3, their expression status could not be found in the Pancreatic Cancer Database." (PMID 28418924, 2017).
cancer (3 papers, 2016 to 2022). A tumor composed of atypical neoplastic, often pleomorphic cells that invade other tissues. "Therefore, future studies are warranted to elucidate the expression pattern of SLCO1B7 with ct-SLCO1B3 in cancer to elucidate whether a functional LST-3TM12 protein in HGSOC exits and to gain information to its relation to drug resistance and cancer progression." (PMID 30131693, 2018). "However, we did not observe significant co-expression of SLCO1B7 with SLCO1B3 in our cohort, but co-expression with the cancer-specific variant might be possible." (PMID 30131693, 2018).
tumor (1 paper, 2023). "The analysis revealed significant correlations between expression of circ-SLCO1B7/ miR-139-5p and tumor size, T grade, N grade, and differentiation." (PMID 37564195, 2023).
SLCO1B7 also shares sentences with these, for which no sentence is quoted: Epileptic encephalopathy (1 paper); myopathy (1).